PML (PML nuclear body scaffold)
Diseases named in the same sentence as PML in open-access papers (continued):
Sharing a sentence is not in itself a finding about the gene and the disease.
infection (continued). "In contrast to proteins for which phosphorylation was enhanced during infection, PML protein only was detected in control cell lysates, which is consistent with the presence of PML phosphopeptides in control, but not infected, MS analyses." (PMID 24068923, 2013). "For HSV and HCMV, PML degradation limits an intrinsic host response to infection that represses viral gene expression." (PMID 24068923, 2013). "Remarkably, as observed with As2O3, infection with EMCV results in recruitment of PML toward the nuclear matrix followed by its degradation." (PMID 23734343, 2013). "Although EMCV replication occurs in the cytoplasm, it has been reported that, during the early steps of infection or in transfected cells, the viral protease 3C (3Cpro) and the 3D polymerase (3Dpol) colocalize with PML in NBs." (PMID 23734343, 2013). "Historically, the first evidence of the interaction between viruses and PML came from the observation that infection of cells with Herpes virus 1 (HSV-1) led to the rapid disruption of the PML-NBs." (PMID 23526763, 2013). "Increases in the PML signal were observed in both neurons and accessory cells and, importantly, were restricted to infected TG, demonstrating that the increase in the PML signal resulted from the on-going infection." (PMID 22912575, 2012). "Our 3D reconstructions confirmed that most PML nuclear bodies in VZV infected cells expressing endogenous PML are disassembled efficiently during the course of infection." (PMID 22685402, 2012). "Incontrast to non-infected cells, we observed a trend towards intranucleardisplacement of Daxx from PML-NBs and PML clustering following infection (red arrows), whichcould be clearly distinguished from Daxx spots in uninfected cells." (PMID 22427750, 2012). "It was recently reported by some of the co-authors of this work that thetransient PML-NBs resident factor Daxx suppressed Ad replication and wasdegraded late in the infection cycle." (PMID 22427750, 2012). "Infection of PML-knockout mice demonstrates that PML/PML-NBs are involved in virus nuclear pattern acquisition, and negatively regulate the expression of the LAT." (PMID 22912575, 2012). "Given the important role of PML NBs in innate immunity it is to be expected that viruses would need to overcome this defense in order to establish a productive infection." (PMID 23795346, 2012). "Similar to what we observe early in infection,transfected protein VI also displaces Daxx from PML-NBs and translocates it into thecytoplasm." (PMID 22427750, 2012). "We show that the virus likely targets PML NBs early in infection to gain access to DNA repair factors." (PMID 21998700, 2011). "Infection of control cells resulted in a significant localization of SUMO-1 and SUMO-2/3 conjugates, as well as PML, to sites closely associated with viral genomes (shNeg panels)." (PMID 21949651, 2011). "While this does not necessarily reflect ND10 protein recruitment, IE2 also forms foci during infection of PML depleted cells, and this stimulates the transient appearance of closely associated accumulations of hDaxx and co-localizing Sp100." (PMID 22355446, 2011). "Lysine to arginine mutations at residues 160 and 490 (K160/490R), the two major SUMO modification sites, were expressed in control and PML-depleted cells and monitored for their respective stabilities during infection." (PMID 21949651, 2011). "We stained HCMV IE1 (green, B and E) and ND10 (anti-PML in red, A and D) at five hours post-infection (hpi) of the HCMV UL131-repaired AD169 (vDW215-BADrUL131) in NIH3T3 cells (A–C) and of the wt (wild type) MCMV in human cells (D–F)." (PMID 21552525, 2011).
infection (continued). "We suggest that the role of NC entrapment by PML cages in skin is important for the modulation of the infection by the innate, interferon-induced response through restriction of cell-cell spread." (PMID 21304940, 2011). "Here we show that PML knockdown inhibits viral replication in vivo, thus indicating a positive role of PML early in infection." (PMID 21998700, 2011). "Secondly, short interfering RNA (siRNA)-mediated depletion of PML results in markedly increased IE gene expression and more efficient initiation of productive infection." (PMID 21994568, 2009). "ICP0 localizes near or at PML NBs early in infection and appears to facilitate the dispersal of nuclear PML and the proteosome-dependent degradation of high molecular weight PML isoforms." (PMID 18509536, 2008). "While IE1 was not in our screen, we have identified 10 additional CMV proteins with similar effects on PML disruption, which vary in their degree of importance for infection." (PMID 18617993, 2008). "In contrast to wild-type infection, exposing HeLa cells to ORF75c− virions made their PML bodies more prominent." (PMID 18648660, 2008). "Namely, ICP0 appears to migrate from the cytoplasm to target nuclear PML and PML NBs relatively early in infection." (PMID 18509536, 2008). "Overexpression of TRIM19 (PML) is reported to confer resistance to infection by vesicular stomatitis virus and influenza A virus." (PMID 16460575, 2006). "However, the function of these bodies in infection differs depending on the viruses: for some, PML-NBs possess intrinsic antiviral properties, while for others, they support viral replication." (PMID 41157668, 2025). "Therefore, using microscopy, we observed the formation of nuclear HSC70 puncta that were distinct from PML puncta at 8 hpi following infection with ICP0-RF HSV-1." (PMID 40577456, 2025). "In mouse models of HSV-1 infection, the viral genome localized at PML-NBs during acute phases of infection and subsequent latent phases in neurons, and the depletion of PML affected the expression of latency-associated transcripts (LAT) and the subsequent establishment of latency." (PMID 38399958, 2024). "Furthermore, confocal microscopy images indicated the degradation of the PML nuclear body after NS1 transfection which corroborated with results obtained in the infection (18 hpi) model." (PMID 38166085, 2024). "Upon infection with IE1-deficient HCMV, PML-NBs rearrange into enlarged PML cages." (PMID 39551864, 2024). "In addition, this study also reported that IFI16 is targeted to PML-NBs following infection with an ICP0 mutant HSV-1." (PMID 38399958, 2024). "In accordance with the immunofluorescence data for treatment directly after infection, a decrease in PML-NB number upon treatment with 2 and 4 μM ATO could be observed at 3 and 6 dpt (ad, and ah)." (PMID 38567974, 2024). "Interestingly, the antiviral functions of PML NBs were identified via the observation that they rapidly disappear soon after infection by viruses with large DNA genomes." (PMID 37127643, 2023). "Interestingly, an increased number of PML NBs was detected in JCPyV-infected cells early after infection." (PMID 37127643, 2023). "During infection, the protein is localized to PML NBs and interacts with PML-II." (PMID 37127643, 2023). "PML is primarily upregulated in infection by type I and type II IFNs." (PMID 37022178, 2023). "BKPyV alters the number and size of PML NBs during infection." (PMID 37127643, 2023).
infection (continued). "Since strongly enlarged PML foci were found particularly after infection with MOIs greater than 1, which allow lytic replication and viral early/late gene expression, the question arose whether viral DNA replication is required for their formation." (PMID 35319461, 2022). "While overexpression of PML isoforms resulted in unspecific aggregates in non-infected cells, infection with IE1-deficient HCMV induced a re-organization of all PML isoforms into ring-shaped structures." (PMID 35319461, 2022). "To get further evidence for an antiviral function of PML cages, we tested whether disruption of PML cages can abrogate the repression of entrapped genomes and promote lytic infection." (PMID 35319461, 2022). "Having observed that IFN signaling plays an important role for the formation of PML cages during infection, we next analyzed whether IFN treatment alone can induce such effects in HFF cells." (PMID 35319461, 2022). "Therefore, the ability of the virus to efficiently generate PML-tracks composed out of PML-I provides the explanation for PML-I infection promoting effect in HepG2 cells." (PMID 35699431, 2022). "Notably, HCMVΔIE1 input genomes remain associated with PML-NBs and can still be detected in a condensed state at the inner rim of PML cages at 3 days after low multiplicity infection (MOI = 0.1)." (PMID 35319461, 2022). "Therefore, it appears likely that PML cages form as a response to continuous interferon and DNA damage signaling during HCMVΔIE1 infection, initiated by incoming viral DNA and enhanced by viral DNA replication, leading to a further enlargement of PML spheres." (PMID 35319461, 2022). "In order to evaluate whether formation of PML cages is also induced in a MOI-dependent manner, we performed a series of infection experiments with increasing amounts of IE1-deficient HCMV (MOI of 0.1–10 IEU/cell)." (PMID 35319461, 2022). "Moreover, our group recently showed that the therapeutic agent, arsenic trioxide (ATO), efficiently inhibits HAdV infection by modulation of PML-NBs, emphasizing the importance of complete understanding of the PML role in infection." (PMID 35699431, 2022). "So far, it has only been reported that PML-II promotes E1A mediated HAdV transcription, whereas the fate and function of the other PML splice variants during infection is not investigated." (PMID 35699431, 2022). "However, PML and PML-NBs are targeted and modified by viral proteins to overcome their antiviral activities during infection." (PMID 34888375, 2021). "Since both the expression of humIE1CORE and the shRNA mediated depletion of PML in human fibroblasts were sufficient to elicit productive RCMV replication, we conclude that the PML-NB disrupting activity of IE1 plays a major role to allow for permissive infection." (PMID 34370791, 2021). "Therefore, in general, herpesviruses exploit the molecular assembly within PML NBs to heterochromatinize their genome and to go into the latent phase of infection." (PMID 34513832, 2021). "Due to the structural similarity of primate and rat CMV IE1, we next investigated whether IE1 proteins can counteract the PML-based defense during cross-species infection." (PMID 34370791, 2021). "Infection with an ICP0 null mutant results in a more persistent association between HSV-1 genome and PML NBs, whereas expression of ICP0 triggers dismantling of PML NB associated proteins from vDNA." (PMID 34513832, 2021). "While infection with OSU strain enhanced the area of PML NBs as oblong structures, infection with other SA11–4F-like rotaviruses (SA11-L2, SNF, and SRF) and OSU-like virus (SDF) resulted in a substantial reduction in the number of PML NBs compared to uninfected cells." (PMID 33807177, 2021). "This indicates that the cellular restriction factor PML forms an important barrier for cross-species infection of cytomegaloviruses that might be overcome by adaptation of IE1 protein function." (PMID 34370791, 2021).
infection (continued). "Since E4 viral proteins can induce degradation or mislocalization of host proteins such as the MRN complex and PML, we hypothesized that antiviral proteins may be recruited to viral genomes during AdΔE4 infection." (PMID 34463575, 2021). "Viral DNA must undergo a few rounds of unlicensed DNA amplification to establish a low copy number of viral genomes in the cell nucleus, and the PML bodies might be a permissible nuclear location to initiate infection." (PMID 34578427, 2021). "Overexpression of PML in CHO cells increased the resistance to infection of VSV." (PMID 31979016, 2020). "We hypothesize that during infection, most E2A will be bound to HAdV DNA, masking its DNA binding domain and potentially also other surfaces that might mediate direct interactions with PML, so only SUMO-SIM interactions are seen." (PMID 32184235, 2020). "Furthermore, it is tempting to assume that this protection of the viral genome by PML protein then results in efficient viral transcription and establishment of infection." (PMID 32154186, 2020). "In contrast, human papillomavirus (HPV) infection requires the presence of PML protein suggesting that PML NBs may be essential to establish infection." (PMID 32154186, 2020). "Moreover, by comparing the volume of PML foci in non-infected (NI) relative to HHV-6B infected MOLT-3 cells we conclude that the mean volume of PML foci is enhanced after 72h of infection." (PMID 32658923, 2020). "Transcriptional enrichment of the PML pathway was observed in infected cells, peaking during productive infection (q‐value for enriched genes at 7 dpi after correction for multiple testing = 0.0007; first percentile of 217 pathways in the Biocarta pathway collection)." (PMID 32157726, 2020). "This suggests that HSV-1 may have hijacked the PML stress response function for successful infection." (PMID 32545507, 2020). "This RC/infection-mediated change of the localization of SUMO proteins involved in the E2A/PML interaction could explain a change in the binding capacity." (PMID 32184235, 2020). "To investigate the effects of E2A SUMOylation on the organization of HAdV RCs and PML-NBs during infection, we performed immunofluorescence microscopy on cells infected with HAdV wt and HAdV E2A SCM to determine the morphology and abundance of these two structures." (PMID 32184235, 2020). "However, it is clear that many DNA viruses disrupt or manipulate PML NBs to promote successful infection." (PMID 32013091, 2020). "Importantly, the increase in both Ly-6Chi Mφ and PML induced by infection (SPF mice) was much greater as compared to the innate memory effect induced by skin colonization (sDMDMm2)." (PMID 32639232, 2020). "Nevertheless, our observations are in contrast with the stable recruitment phenotypes reported for HIRA at PML-NBs in response to infection with replication-defective herpesviruses at 2–6 days post-infection (; discussed further below) or IFN stimulation 8–24 hours post-treatment." (PMID 30901352, 2019). "The importance of PML-NBs in the regulation of intracellular immunity is highlighted by the fact that many DNA and RNA viruses have evolved independent strategies to disrupt these dynamic nuclear sub-domains during infection." (PMID 30901352, 2019). "We therefore sought to investigate the spatiotemporal kinetics of HIRA localization to infecting HSV-1 genomes and PML-NBs in the sequential regulation of intrinsic and innate immune defences under productive lytic infection conditions pertinent to a clinical setting." (PMID 30901352, 2019). "Collectively, our data demonstrate that HIRA recruitment to PML-NBs in the context of lytic replication in diploid cells represents a sequential step in the paracrine activation of innate immune defences to prime cells for imminent infection." (PMID 30901352, 2019). "Interestingly, PML also forms similar inclusions that contain viral capsid proteins following infection with varicella-zoster virus." (PMID 31416160, 2019).
infection (continued). "However, the stable localization of HIRA at PML-NBs was only observed at comparatively late times post-infection (2–6 days;), which is atypical of intrinsic PML-NB host factors that silence viral gene expression from the outset of nuclear infection." (PMID 30901352, 2019). "In addition, we observed again that PML protein expression is strongly increased upon infection with the KSHV.WT virus but much less after infection with the vIRF2 knockout virus (PML panel)." (PMID 31059555, 2019). "It is attractive to speculate that HPV exploits PML NBs to regulate early transcription, PML protein allowing early transcription to establish infection and delayed Sp100 recruitment helping transition to the maintenance phase." (PMID 30802273, 2019). "NBs contain SP100/SP140 family and PML (promyelocytic leukemia) proteins, and many NB proteins have been revealed to play a key role in the regulation of transcription, cell division, apoptosis, senescence, and response to DNA damage or infection." (PMID 29642903, 2018). "As previously reported, the ORF75CΔ648–659 mutation ablated PML degradation upon infection of primary fibroblasts, but this did not reduce viral protein expression or replication of the single 75CΔ648–649 mutant." (PMID 29390024, 2018). "It is possible that DAXX is restrictive while in complex with ATRX but at a later stage of infection, after dispersion of PML-NBs and degradation of ATRX, DAXX may promote HSV gene expression or replication." (PMID 30465651, 2018). "Of the interferon regulatory factor (IRF) genes annotated in KEGG, expression of IRF7 was significantly upregulated, and interestingly, all downstream transcriptional targets of IRF9 annotated in KEGG (MX1, OAS genes, ADAR, and PML) were consistently upregulated during acute infection." (PMID 30150281, 2018). "In addition, to further confirm these observations, HeLa cells were transfected with an empty vector (pEGFP-C1) or plasmids expressing each PML isoform (PMLI–VI) followed by infection with EV71 (MOI = 5) for 24 h." (PMID 29922292, 2018). "Infection by Listeria affects PML SUMOylation and multimerization." (PMID 28074026, 2017). "Here, we show that PML restricts infection by the pathogenic bacterium Listeria monocytogenes but not by Salmonella enterica serovar Typhimurium." (PMID 28074026, 2017). "Likewise, much remains to be discovered regarding preferential remodeling of PML components like Daxx and Sp100 immediately after mitotic translocation of L2/vDNA, and the consequences of this remodeling for infection, immune evasion, and viral persistence." (PMID 29207511, 2017). "In order to explore the link between LLO-producing Listeria and PML, we assessed whether infection leads to a modification of PML SUMOylation." (PMID 28074026, 2017). "In conclusion, our transcriptomic and proteomic screens identified a network of genes induced upon infection in a PML-dependent manner and highlighted a first role of PML in antibacterial responses, acting as a master regulator of genes involved in immunity against Listeria." (PMID 28074026, 2017). "Finally, the precise role(s) of virion-derived L2 in the remodeling of PML bodies, establishment of infection, initial viral gene expression, and potential immunoevasion all represent exciting avenues of future endeavors." (PMID 29207511, 2017). "In addition, the earlier work by Ishov and Maul showed, using immuno-FISH, that only a small portion of incoming HCMV genomes localize at PML-NBs at two hours post-infection (hpi)." (PMID 27782081, 2016). "It was shown in mice models that HSV-1 genomes locate at PML-NBs during acute phases of infection and during subsequent latent phases in neurons, and that absence of PML affects the expression of latency associated transcripts (LAT)." (PMID 27782081, 2016).